IL6 (interleukin 6)
Diseases named in the same sentence as IL6 in open-access papers (continued):
Sharing a sentence is not in itself a finding about the gene and the disease.
gastric ulcer (continued). "TNF-α and IL-6 levels are increased in ethanol-induced gastric ulcers, but the harmful effect of these cytokines can be reversed by the administration of natural products with anti-inflammatory activity." (PMID 25954316, 2015). "It has been proposed that TNF-α and IL-6 are critical in controlling the graveness of gastric ulcer and the release of these cytokines can lead to the accumulation of ROS in the mitochondria resulting to oxidative stress." (PMID 26694339, 2015). "It was suggested that the pro-inflammatory cytokines TNF-α and IL-6 are important in regulating the severity of gastric ulcers." (PMID 24466200, 2014). "Effect of menthol (50 mg/kg) on the levels of TNF-α, IL-6 and IL-10 cytokines in rat stomachs with ethanol-induced gastric ulcers after treatment with vehicle, carbenoxolone (100 mg/kg) or menthol (50 mg/kg)." (PMID 24466200, 2014). "IL-6 has also been identified as a major driver of gastric ulcer development." (PMID 39861107, 2025). "Accordingly, oral TA treatment of mice with ethanol-induced and ethanol/HCl-induced gastric ulcers exhibited gastroprotective effects, which were associated with a decrease in TNF-α, IL-1β and IL-6 protein levels and an increase in IL-10 protein levels in gastric tissue." (PMID 40427543, 2025). "CHE also significantly reduces the gastric ulcer index, inhibits NO concentration, IL-6 and TNF-α levels in serum and gastric mucosa of mice with gastric ulcers, while markedly attenuating the overexpression of NF-κB in the gastric mucosa to exert anti-inflammatory activity." (PMID 39239653, 2024). "Compared with the control group, the expression levels of IL-1β, IL-6, and TNF-α in the gastric tissues of rats in the model group were significantly higher (p < 0.01), suggesting that the increased levels of inflammatory cytokines (IL-1β, IL-6, and TNF-α) were associated with gastric ulcers." (PMID 38398633, 2024). "Having confirmed that numerous biological agents able to diminish the levels of pro-inflammatory cytokines such as TNF-α, IL-1β, and IL-6, could potentially exhibit effectiveness in the management of gastric ulceration." (PMID 38355510, 2024). "Moreover, OM pretreatment improved indomethacin-induced gastric ulcer in rats where it decreased IL-6, TNF-α, and oxidative markers and improved mucosal contents of cyclooxygenase-1 and prostaglandin E2." (PMID 37255094, 2023). "In addition, the levels of the inflammatory factors of IL-6 also dramatically increased in alcohol-induced gastric ulcers, leading to the breakdown of connexin and further exacerbating gastric mucosal damage." (PMID 38259271, 2023). "Then we evaluated the levels of the mayor inflammatory cytokines responsible for driving the inflammatory response in gastric ulcer such as IL-1β, IL-6 and TNF-α40." (PMID 33574472, 2021). "During ethanol-induced gastric ulcer formation, NF-κB governs the increased transcription of genes encoding inducible nitric oxide synthase (iNOS), COX-2, and inflammatory cytokines including tumor necrosis factor-α (TNF-α), interleukin (IL)-6, and IL-1β." (PMID 34630623, 2021). "Previous research showed that gastric ulcers caused by ethanol may activate the innate immune system and upregulate the levels of proinflammatory cytokines, such as TNF-α, IL-1β, and IL-6." (PMID 34580595, 2021). "It is believed that drugs that could effectively treat or protect against gastric ulcer should have the ability to suppress the secretion of interleukin-6 (IL-6), tumor necrosis factor-alpha (TNF-α), scavenge ROS and/or stimulate mucosal defense mechanism." (PMID 26694339, 2015). "An elevated level of IL-6 activates neutrophils, lymphocytes and monocytes/macrophages at the inflammatory site, triggering the oxidative pathways responsible for local tissue damage in gastric ulcer disease." (PMID 24466200, 2014).
gastric ulcer (continued). "Previous research showed that gastric ulcers caused by ethanol intake may trigger and activate the inflammatory system, accompanied by up-regulated levels of pro-inflammatory cytokines, such as TNF-α, IL-6, IL-12, and IL-18." (PMID 40283949, 2025). "Therefore, by reducing TNF-α, IL-6, and IL-1β expression, A. graveolens may be considered as an alternative agent for treating gastric ulcer patients." (PMID 38355510, 2024). "However, the administration of OLE and OLR to gastric-ulcer rats protected from inflammation in gastric tissues and showed a potential decrease of TNF-α (by 21 and 17%, respectively) and IL-6 (54 and 47%, respectively) as compared to untreated gastric-ulcer rat." (PMID 38911236, 2024). "In addition, IL-6 stimulates lymphocytes, macrophages, and neutrophils in the inflammatory region and triggers the oxidative pathway responsible for tissue damage during gastric ulcer." (PMID 36836745, 2023). "Moreover, gastric ulcer indices, histopathological morphology, oxidative stress markers (MDA, GSH, SOD), inflammatory mediators (NO, PGE2), and cytokine gene expression (TNF-α, IL-6, IL-1β, iNOS) were evaluated via enzyme-linked immunosorbent assay (ELISA) and quantitative real-time PCR." (PMID 40361682, 2025). "Cheng, Lu & Yen (2017) reported that gastric ulcers have various processes such as the activation of phospholipase A, COX-2, myeloperoxidase (MPO), and pro-inflammatory cytokines (TNF-α, IL-6, and leptin)." (PMID 38435992, 2024). "Pretreatment with C. citrinus and OME-ameliorated gastric ulceration damage induced by IND, via anti-inflammatory mechanisms, by decreasing MPO, COX-2, and 5-LOX activities and inflammatory cytokines (TNF-α and IL-6)." (PMID 38435992, 2024). "In gastric ulcer models, honey reduced the gastric mucosal malondialdehyde (MDA), IL-1β, IL-6, and TNF-α." (PMID 38045104, 2023). "Both HCl/ethanol- and indomethacin-induced gastric ulcers showed increased TNF-α, IL-6, Evans blue permeation, and PECAM-1, and decreased COX-2, PGE2, occludin, and LPA5 receptor expression levels." (PMID 38069044, 2023). "Meanwhile, chrysin activated peroxisome proliferator activated receptor-γ (PPAR-γ) and lowered the expression of pro-inflammatory marker genes, including TNF-α, IL-6, and CCL3, to fight indomethacin-induced gastric ulcer." (PMID 35008842, 2021). "In the present study, the serum levels IL-6, IL-12, TNF-α, and IFN-γ in the mice with reserpine-induced gastric ulcers were markedly decreased following treatment with insect tea." (PMID 25187847, 2014). "In a previous study, the colonic levels of IL-6, IL-12, TNF-α and IFN-γ in mice with reserpine-induced gastric ulcers were markedly decreased following D. candidum treatment." (PMID 25120640, 2014). "This study investigated the effects of probiotics combined with quadruple therapy on serum levels of tumour necrosis factor-a (TNF-a), interleukin-6 (IL-6), C-reactive protein (CRP), gastrin (GAS), and motilin (MTL) in patients with Helicobacter pylori (Hp)-positive gastric ulcer (GU)." (PMID 41281280, 2025). "This study aimed to explore the clinical efficacy of probiotics plus quadruple therapy on Serum levels of tumour necrosis factor-a (TNF-a), interleukin-6 (IL-6), C-reactive protein (CRP), gastrin (GAS) and motilin (MTL) in treating Helicobacter pylori (Hp)-positive gastric ulcer (GU)." (PMID 41281280, 2025). "For example, studies showed that Dioscorea administration in ethanol-induced gastric ulcer models significantly increased the activity of antioxidant enzymes such as SOD, GPx, and CAT, while reducing pro-inflammatory cytokines like TNF-α, IL-1β, and IL-6." (PMID 41010469, 2025). "Suppression of inflammation (by inhibiting NF-κB & IL-6), oxidative stress, inhibition of apoptosis, and stimulation of TGF-β1 could be other mechanisms in the Phytol/nano-Phytol-induced healing effect of gastric ulcers." (PMID 40644360, 2025).
gastric ulcer (continued). "In addition, the supplementation of OLE or OLR to ethanol-induced gastric ulcer tats inhibits inflammation at the level of gastric tissues, observed by an important inhibition of MPO activity and TNFα and IL6 rates and improvement of NO rate." (PMID 38911236, 2024). "The results confirmed that DOP was effective in reducing the levels of inflammatory factors (IL-1β, IL-6, and TNF-α) in the gastric tissues of rats with gastric ulcers, with the most significant effects observed in the DOP-200 and DOP-400 groups (p < 0.05 or p < 0.01)." (PMID 38398633, 2024). "In a further study, manuka honey was also effective against chronic acetic acid-induced gastric ulcers, and the observed effect was due to antioxidant and anti-inflammatory effects with a significant reduction in mucosal MDA levels, TNF-α, IL-1β, and IL-6 and an increase in IL-10 levels." (PMID 38045104, 2023). "The results of this study showed that MOE could inhibit the levels of proinflammatory cytokines (TNF-α, IL-1β, IL-6) induced by ethanol, suggesting that MOE has an anti-inflammatory effect on ethanol-induced gastric ulcer." (PMID 34159200, 2021). "However, the levels of TNF-α, IL-1β and IL-6 in tissue and GES-1 cell supernatant were significantly decreased, and the corresponding gastric ulcer and mucosal integrity were improved in the Ran and F-AOH groups." (PMID 32871094, 2020). "Furthermore, the serum proinflammatory cytokine IL-1β, IL-6, and TNF-α levels were significantly decreased following the administration of ethyl acetate extract of SP in a gastric ulcer model." (PMID 30116487, 2018). "Another possible mechanism by which manuka honey treats gastric ulcer may be due to inhibition of the proinflammatory cytokines: TNF-α, IL-1β, and IL-6." (PMID 28250794, 2017). "In particular, the mRNA expression of IL-6 and TNF-α in the DOP-200 and DOP-400 groups was significantly decreased, indicating that these groups could effectively inhibit the further deterioration of gastric ulcers." (PMID 38398633, 2024). "It reduced gastric ulcers (GU) by suppressing ethanol-induced nuclear factor-κB (NF-κB) activity and decreasing the levels of nitric oxide (NO), malondialdehyde (MDA), tumor necrosis factor-α (TNF-α), interleukin-6 (IL-6), interleukin-8 (IL-8), and myeloperoxidase (MPO)." (PMID 34769415, 2021). "Pro-inflammatory cytokines like tumor necrosis factor-α (TNF-α), Interleukin-1β (IL-1β), Interleukin-6 (IL-6) and growth factors including insulin like growth factor-1 (IGF-1) play an important role in the pathogenesis of chronic diseases like autoimmune diabetes and gastric ulcers." (PMID 24192345, 2013). "Notably, rats with ethanol-induced gastric ulcers treated using GF and GFC exhibited a non-significant decrease in the levels of IL-6 (10.7% and 11.4%, receptively)." (PMID 31333466, 2019).
acute lung injury (69 papers, 2011 to 2025). A condition of lung damage that is characterized by bilateral pulmonary infiltrates (pulmonary edema) rich in neutrophils, and in the absence of clinical heart failure. "In addition, TNF-α and IL-6, which are strongly induced by PFO, are involved in the development of pathological pain as well as fever, and IL-6, IL-8, and IL-10 are reported to cause acute lung injury/ARDS." (PMID 34385995, 2021). "We evaluated the levels of key cytokines, including TNF-α, IL-6, IL-1β, IL-10, IL-17, IL-22, IFN-γ, and TGF-β1, which play central roles in the inflammatory cascade associated with LPS-induced acute lung injury (ALI)." (PMID 41280422, 2025). "In patients with acute lung injury, sivelestat sodium more effectively reduced IL-6, TNF-α, and CRP levels (in comparison with doxofylline), and significantly increased the oxygenation index at 24 and 72 h." (PMID 40842872, 2025). "Pro-inflammatory cytokines such as TNF-α, IL-6, and IL-1β, coupled with the anti-inflammatory cytokine IL-10, have important functions in the inflammatory process that leads to the advancement of acute lung injury (ALI)." (PMID 38732622, 2024). "This study focuses on developing a cholesterol-conjugated anti-Il6 siRNA and the evaluation of its potency for the potential treatment of inflammatory diseases using the example of acute lung injury (ALI)." (PMID 38727303, 2024). "TGFβ1 blocks endotoxin-induced hypotension and improves survival in rat models, it decreases the number of neutrophils during the onset of LPS-induced acute lung injury and promotes the release of IL-6 from mast cells, which promotes neutrophil clearance." (PMID 37875957, 2023). "It was reported that overexpression of miR-146a suppresses the production and secretion of TNF-α, IL-6, and IL-1β to inhibit the development of LPS-induced acute lung injury." (PMID 35112981, 2022). "DHA was previously reported to hinder the production of proinflammatory cytokines IL-1β, TNF-α, and IL-6 via regulating NF-κB signaling in acute lung injury (ALI)." (PMID 34956376, 2021). "GAS6, IL-6 and IL-8 concentrations are increased in septic patients who develop acute lung injury (ALI;41." (PMID 34344929, 2021). "A previous study demonstrated that thymol inhibits TNF-α and IL-6 production via the nuclear factor-kappa B (NF-κB) signaling pathway in mice with an LPS-induced acute lung injury." (PMID 31936809, 2020). "Recent studies have been growing interest in the IL-6-knockout mice model, which the deletion of the IL-6 gene leads to prevent lung inflammation in an acute lung injury mouse model, and protects their mortality as well." (PMID 30142934, 2018). "A previous study found that IL-6 provides a protective effect in hyperoxic acute lung injury and VILI by reducing mortality, protein leakage, and endothelial and epithelial membrane injury through decreasing cell death and DNA fragmentation." (PMID 23822633, 2013). "ROS drive modifications of IκB proteins, leading to their degradation and allowing active NF-κB translocation to the nucleus and inducing inflammatory cytokine release, such as (TNF)-α, IL-1β, and IL-6, which are involved in the inflammatory process of acute lung injury (ALI)." (PMID 37569801, 2023). "In addition, nobiletin exhibited protective effects in decreasing the production of TNF-α, IL-6 via restraining activation of NF-κB signaling in the LPS-induced acute lung injury mice model and LPS-stimulated A549 cells." (PMID 36387362, 2022). "In addition, soluble IL-1β bioactivity and autocrine IL-1β-dependent IL-6 up-regulation are critical initiators of fibroblast activation and proliferation that likely play a role in the fibroproliferative response in human acute lung injury." (PMID 21423633, 2011). "Kajiichigoside F1 and rosamultin were found to mitigate alveolar inflammation in mice with acute lung injury (ALI) by effectively reducing the expression of the pro-inflammatory cytokines TNF-α and IL-6." (PMID 40006066, 2025).
acute lung injury (continued). "This subset has been shown to suppress pro-inflammatory cytokines such as IL-6, G-CSF, and MCP-1, thereby limiting the accumulation of Ly6c hi monocytes, as demonstrated in a bleomycin-induced acute lung injury model." (PMID 40631071, 2025). "Treatment with COST dramatically lowered IL-6 and TNF-α levels and improved lipoteichoic acid (LTA)-induced inflammatory response in an acute lung injury mouse model." (PMID 38629103, 2024). "AS-IV decreased the levels of TNF-α, IL-6, and IL-1β in serum and BALF of mice with Acute lung injury (ALI)." (PMID 38954702, 2024). "Peritoneal injection of MOTS‐c was reported to reduce the basal levels of circulating IL‐6 and TNF‐α in mice fed with a normal diet and inhibit systemic and tissue inflammatory response in lipopolysaccharide (LPS)‐induced acute lung injury mouse model." (PMID 36156853, 2022). "In a mouse model of acute lung injury (ALI), Eda-Bor significantly lowered TNF-α and IL-6 levels in serum and bronchoalveolar lavage fluid and inhibited NF-κB activation." (PMID 36110124, 2022). "In acute lung injury (ALI), Met also reduces the number of inflammatory cells and expression of pro‐inflammatory cytokines such as TNF‐α, IL‐1β, and IL‐6." (PMID 34473417, 2021). "Nilotinib was also reported to reduce IL-6, IL-1β, and TNF-α levels in mice of bleomycin-induced acute lung injury model." (PMID 31293574, 2019). "NF-κB activation is a critical transcription factor required for the maximal expression of many inflammatory cytokines and chemokines (e.g., TNF-α, IL-1β, IL-6, and MIP-2) involved in the pathogenesis of acute lung injury." (PMID 23710113, 2013). "XBJ was also found to inhibit IL-6 and TNF-α secretion in mice with lipopolysaccharide-induced acute lung injury (ALI) and restore the acquired immune suppression due to overactive proinflammatory cytokine productions in patients with MODS." (PMID 24369483, 2013). "An increasing number of studies have shown that in animal models of ischemia-reperfusion (I/R) and acute lung injury (ALI), NGR1 attenuates the expression levels of the inflammatory factors IL-6, TNF-α, and IL-1β and attenuates injury, leading to interventional protection against the disease." (PMID 38109303, 2023). "Our study demonstrated for the first time that ICD ameliorates IL-6 expression in LPS-induced bone marrow-derived macrophages activation in vitro and LPS-induced acute lung injury in mice, and there is no obvious toxicity in vivo." (PMID 36902060, 2023). "Compound 4a inhibits NO synthesis and IL-6 secretion in murine macrophages without immunotoxicity and alleviates neutrophil infiltration, edema, and tissue lesions in a model of LPS-induced acute lung injury." (PMID 36295082, 2022). "In addition, in a mouse model induced by LPS, we determined that sino reduced the lung index and the levels of myeloperoxidase (MPO), NO, IL-6 and TNF-α in lung tissues and bronchoalveolar lavage fluid (BALF) in acute lung injury (ALI)." (PMID 34801005, 2021). "Increased miR-150 decreases neutrophil counts and production of inflammatory cytokines IL-1β, IL-6, and TNF-α along with levels of total protein, albumin and IgM in the BAL fluid in LPS-induced acute lung injury mice in vivo, as well as alleviating LPS-induced A549 cell apoptosis in vitro." (PMID 32315984, 2020). "DA could significantly reduce the level of IL-1β, IL-6 and TNF-α in the bronchoalveolar lavage fluid of the LPS-induced acute lung injury mouse." (PMID 26223251, 2015). "Interleukin-6, interleukin-8, surfactant protein D, and soluble tumor necrosis factor receptor I/II (sTNFr I/II), as well as ICAM-1 and VWF, have been found to be elevated in patients with acute lung injury, and their levels fluctuate rapidly in response to different ventilation strategies." (PMID 39408067, 2024).
acute lung injury (continued). "Furthermore, streptochlorin suppressed the infiltration of immune cells such as neutrophils into the lung and proinflammatory cytokine production such as IL-6 and TNF-α in broncho-alveolar lavage fluid (BALF) in the LPS-induced acute lung injury (ALI) mouse model." (PMID 25822875, 2015).